NOTCH1 (notch receptor 1)
Diseases named in the same sentence as NOTCH1 in open-access papers (continued):
Sharing a sentence is not in itself a finding about the gene and the disease.
ependymoma (5 papers, 2017 to 2021). A WHO grade II, slow growing tumor of children and young adults, usually located intraventricularly. "Previous studies in pediatric ependymoma reported, at recurrence, frequent gains of chromosome 9q33-34 region, i.e. the genomic region of NOTCH1 and Tenascin-C (TNC), associated with the overexpression of TNC." (PMID 28617804, 2017). "Notably, the Notch pathway is implicated in ependymoma oncogenesis, and NOTCH1 mutations have been described to present in 8.3% of pediatric ependymomas samples in one study." (PMID 31480400, 2019). "Last, we found that FGFRis had a central impact on multiple cell biological processes including lipid and RNA metabolism as well as Notch1 or PD-1 signaling, some of which have previously been described for being deregulated or hyperactivated in ependymoma." (PMID 34046693, 2021). "Albeit molecularly heterogeneous, ependymomas share common biological and phenotypic characteristics, beyond histological features, for example Notch-1 pathway activation or putative cell of origin." (PMID 28617804, 2017). "It was suggested that two potential oncogenes, NOTCH1 and Tenascin‐C, located on 9qter and found to be overexpressed might play a role in ependymoma progression." (PMID 32633004, 2021). "NOTCH1 and GPSM1 encode membrane proteins critical for Notch signaling and G-protein signaling, respectively, suggesting the involvement of these signaling pathways in ependymoma development in addition to NF-κB pathway that has received the most attention." (PMID 32909151, 2020).
injury (5 papers, 2017 to 2024). Damage inflicted on the body as the direct or indirect result of an external force, with or without disruption of structural continuity. "Research has also shown that PHC can alleviate apoptosis and endoplasmic reticulum stress and trigger the Hes1/Notch1 pathway, effectively mitigating the effects of lipopolysaccharide-induced acute lung injury." (PMID 38671448, 2024). "Here, we report that myeloid Notch1 signaling regulates the NLRP3-driven inflammatory response in ischemia/reperfusion (IR)-induced liver injury." (PMID 31673056, 2020). "Meanwhile, an in vivo study of Qi showed that the overexpression of Notch1 or Jagged1 in the Notch signaling pathway enhances the migration, invasiveness, and angiogenic ability of endothelial progenitor cells in a rat model of traumatic brain injury." (PMID 35449809, 2022). "A recent study demonstrated that Notch1 signaling promoted HSF1 activation, which in turn inhibited NLRP3 function and hepatocellular apoptosis, leading to the alleviation of I/R-induced liver injury." (PMID 34504645, 2021).
ischemic heart disease (5 papers, 2013 to 2024). "While earlier studies have reported the involvement of Notch1 in coronary heart disease, there is little information on the associations of Notch1 levels with either AMI or CCS." (PMID 38841263, 2024). "However, Notch1 is also linked to coronary heart disease, including both AMI and CCS." (PMID 38841263, 2024). "In addition, this is the first case to provide evidence between NOTCH1 genetic disorder and hypoplastic coronary artery disease in the clinic." (PMID 32871987, 2020). "Notch1 signaling may represent a potential new pharmacologic mimic for cardioprotection of ischemic heart disease." (PMID 24098939, 2013). "However, details of the relationship between Notch1 and coronary heart disease require elucidation." (PMID 38841263, 2024). "Intriguingly, a recent study by our group found that Notch1/Hes1 activation preserved thioredoxin activity and reduced MI/R injury in an acute hyperglycemic animal model, indicating that Notch1/Hes1 signaling might play a role in ischemic heart disease under diabetic condition." (PMID 29636838, 2018). "Furthermore, we proposed that Notch1/Hes1 and its downstream Pten/Akt pathway might serve as novel therapeutic targets for treating ischemic heart disease in diabetic setting." (PMID 29636838, 2018).
lung adenoma (5 papers, 2012 to 2019). A benign, well circumscribed epithelial neoplasm that arises from the bronchus or the lung parenchyma. "The expression of activated Notch1 (NICD1) in the pulmonary epithelium of mice can induce lung adenomas." (PMID 29416684, 2018). "Increased frequency of Notch1 activation can induce lung adenoma formation and enable progression to Ade and metastases." (PMID 28061457, 2017). "Moreover, overexpression of constitutively activated Notch1 directly participates in lung carcinogenesis; it induces lung adenomas in mice which progress to ADCs in cooperation with Myc overexpression." (PMID 25004243, 2014). "Notch1 overexpression in the mouse lung alveolar epithelium, driven by the Clara cell specific protein (CCSP) promoter, leads to pulmonary adenomas that progress to ADCs when crossed with conditional Myc overexpression." (PMID 25004243, 2014).
lupus (5 papers, 2016 to 2023). "For example, MSC transplantation alleviates early brain injury in subarachnoid hemorrhage and improves osteopenia in lupus by suppressing Notch1 signaling." (PMID 32493480, 2020). "Our results indicate that Notch1-Hes-1 signaling controls TLR7-induced autophagic death of macrophage via regulation of P62 in mice with lupus." (PMID 27537524, 2016). "In addition, MSC transplantation has been reported to suppress Notch1 signaling in various systemic diseases, such as ischemic stroke, inflammatory bowel disease, lupus, and brain injury." (PMID 32493480, 2020). "The abnormal activation of Notch1 signaling plays an important role in the pathogenesis of systemic lupus erythematosus (SLE), which also promote the MDSC differentiation process." (PMID 37547175, 2023).
Osteopenia (5 papers, 2019 to 2023). Osteopenia is a term to define bone density that is not normal but also not as low as osteoporosis. "Notch1 activation in mesenchymal stem cells and mature osteoblasts caused severe osteopenia and resulted in defective bone structure formation." (PMID 34069142, 2021). "It is speculated that APOA1, FBN1, NOTCH1, SYT7 and KLF10 played key roles in regulating bone metabolic balance and in reversible osteopenia after PAOO, which might be involved in the accelerated tooth movement." (PMID 38012627, 2023). "It is speculated that APOA1, FBN1, NOTCH1, SYT7 and KLF10 play key roles in regulating bone metabolic balance and in reversible osteopenia after PAOO, which might be involved in the accelerated tooth movement." (PMID 38012627, 2023).
retinoblastoma (5 papers, 2016 to 2025). A malignant tumor that originates in the nuclear layer of the retina. "It is known that Pax5 inhibits the growth of retinoblastoma by inhibiting the activity of the Notch1 signaling pathway." (PMID 41150792, 2025). "A recent study showed that microRNA MiR-433 inhibits retinoblastoma growth by suppressing Notch1 and PAX6 expression." (PMID 27661116, 2016). "Furthermore, miR-433 inhibits retinoblastoma by suppressing the expression levels of notch homolog 1 (Notch1) and paired box protein Pax-6 (PAX6)." (PMID 28402262, 2017). "Meanwhile, if oscillatory gene expression in some undifferentiated cells/RPCs does not stop due to pathological events (e.g., mutations in genes regulating the stability of mRNA and proteins of genes like Notch1, Hes1, Dll1, Ascl1, Neurog2, etc.), these cells may begin retinoblastoma formation." (PMID 31607861, 2019). "ROR higher levels activates Notch1 expression via negative regulation of miR-32, stimulating EMT in retinoblastoma." (PMID 36229883, 2022). "Notch pathway components were present in WERI Rb1 and Y79 retinoblastoma lines, with Jag2 and DLL4 more highly expressed than other ligands, and Notch1 and Notch2 more abundant than Notch3." (PMID 27661116, 2016). "HOTAIR serves as tumor promoter, increasing Notch1 and JAG1 expressions in retinoblastoma." (PMID 36229883, 2022).
stomach adenocarcinoma (5 papers, 2014 to 2020). "Based on the findings, in comparison with normal gastric tissues, gastric adenocarcinoma tissues presented higher expression levels of Notch1/2/3." (PMID 32028262, 2020). "The expression of Notch1, Notch2, Notch3 and Notch4 proteins, which were examined by immunohistochemistry, were higher in the gastric adenocarcinoma tissues than that in the normal gastric tissues." (PMID 32028262, 2020). "Furthermore, the activation of Notch1 signaling promoted tumor progression of stomach adenocarcinoma SC-M1 cells through induction of COX-2 (cyclooxygenase-2 (expression." (PMID 32704077, 2020). "The intracellular domains of Notch1 and Notch2 receptors (N1ICD and N2ICD, respectively), promoted cell proliferation and xenografted tumor growth of human stomach adenocarcinoma SC-M1 cells." (PMID 28416750, 2017). "Data obtained from The Cancer Genome Atlas (TCGA) were also analyzed and found that levels of miR-151 and Notch1 and FAK mRNAs were significantly increased in majority of stomach adenocarcinoma samples as compared with normal tissue samples." (PMID 27191259, 2016). "Additionally, Notch1 had a positive correlation with CD4, GATA3 and STAT5B and a negative correlation with CD59 in gastric adenocarcinoma." (PMID 32028262, 2020).
ulcerative colitis (5 papers, 2013 to 2024). An inflammatory bowel disease involving the mucosal surface of the large intestine and rectum. "We first investigated the cytoplasmic expression of Notch1 in human colorectal adenoma tissues and in ulcerative colitis tissues at the level of protein by using IHC method." (PMID 24312514, 2013). "Overexpression of Notch1 was observed in the dextran sodium sulfate-induced ulcerative colitis in mice." (PMID 24312514, 2013). "In addition, the interplay between inflammation and the NOTCH signaling has been amply reviewed and it has been reported that NOTCH1 and HES1 in co-operation with TNF-α can suppress PPAR-γ to play a crucial role in the pathogenesis of ulcerative colitis." (PMID 36386153, 2022). "In the FFPE (formalin-fixed paraffin-embedded) sections prepared from the colons of ulcerative colitis (UC) and immune-mediated colitis (IRAEC) patients, expression of DCLK1 isoforms correlated positively with Notch1 and negatively with a transcriptional repressor, FoxD3 (Forkhead Box D3)." (PMID 34226497, 2021).
vascular tumors (5 papers, 2011 to 2021). "A recent study employing an elegant genetic model showed that loss of Notch1 caused widespread vascular tumors, particularly in the liver, further underscoring the potential safety concerns associated with continuous blockade of NOTCH1 signaling." (PMID 21824400, 2011). "Recently, it has also been shown that Dll4 or combined Notch1 and -2-inhibition can lead to development of vascular tumors and hepatotoxicity." (PMID 21533193, 2011).
amyloid (4 papers, 2016 to 2022). "To validate the neuroinflammatory potential of Notch1 and amyloid plaques, we performed the triple immunolabeling with the activated microglia marker, CD68 (a–a”)." (PMID 27364742, 2016).
autism (4 papers, 2013 to 2024). Persistent deficits in social interaction and communication and interaction as well as a markedly restricted repertoire of activity and interest as well as repetitive patterns of behavior. "In addition, activated Notch1 cascade stimulates its downstream target NF-κB, which has been linked to autism, as documented from post-mortem tissue analysis of autistic patients showing increased NF-κB expression." (PMID 38137376, 2023). "Although recent studies highlighted crosstalk between RAS and Notch1, few data are available on their link to neuronal disorders, autism, tauopathy, or astrogliosis." (PMID 38137376, 2023). "In a recent study, Yanan Deng reported that inhibition of the Notch pathway using DAPT alleviated autism-like behaviors and reduced NRG1 and phosphorylated ErbB4 levels, suggesting the involvement of the Notch1/Hes1 pathway in regulating the NRG1/ErbB4 pathway in autism." (PMID 38791584, 2024). "Thus, the reduction in the cortical Ang II by AST is considered a novel culprit for deactivating the Notch1/NICD-1/NF-κB axis, which together intermingles to mitigate autism." (PMID 38137376, 2023). "Whether excess sAPPα may potentially be impacting gliosis and abnormal brain development through upregulation of gp130 and consequently gp130-related pathways such as Notch1 and LIF in some individuals with autism remains to be determined." (PMID 23840007, 2013).
bladder tumor (4 papers, 2017 to 2021). "Furthermore, IHC analysis of bladder tumor tissues demonstrated decreased staining for Notch 1, Presenilin 1, Hes1 and Nicastrin in mice treated with CPX-POM." (PMID 34059639, 2021). "NOTCH1 was methylated in a subset of bladder tumors in both the RPCI and TCGA cohorts." (PMID 29242529, 2017). "Moreover, a negative correlation of Mettl14 expression and Notch1 expression was observed in bladder tumors." (PMID 31760940, 2019).
Cirrhosis (4 papers, 2016 to 2025). A chronic disorder of the liver in which liver tissue becomes scarred and is partially replaced by regenerative nodules and fibrotic tissue resulting in loss of liver function. "In in bile duct ligation (BDL) or CCl4-induced mice cirrhosis models, quercetin inhibited stellate cell activation and autophagy via TGF-β1/Smads associated with Notch1 signaling pathway." (PMID 40892759, 2025). "Proteins found to be related to Notch1 expression in cell culture medium were analyzed in serum of patients with cirrhosis, early HCC, advanced HCC or healthy controls." (PMID 27167202, 2016). "Yet, we observed that Jag1, Notch 1, Notch 2, Notch 3, and Hey2 were significantly upregulated in both Ep+CIR and Ep+HCC cells as compared to Ep+NSCs, indicating the appearance of CSC like phenotype during advanced cirrhosis." (PMID 28176469, 2017). "The activation of the purinergic–adenosinergic axis may interface with other key pathways involved in cirrhosis-induced myocardial injury, including TGF-β1 signaling, Notch1 suppression through epigenetic regulation, and the activation of P2X7R-mediated inflammatory pathways." (PMID 40943752, 2025). "Similarly, it is not always possible to obtain tumor tissue samples to test Notch1 expression in patients with HCC on cirrhosis who may display coagulation impairments or other contraindications." (PMID 27167202, 2016).
colorectal adenocarcinoma (4 papers, 2013 to 2021). The most common type of colorectal carcinoma. "The Notch1 gene copy number has been reported to be increased in colorectal adenocarcinomas and to be correlated with aggressive tumor behavior and poor prognosis." (PMID 25936357, 2015). "Interestingly, the importance of intestinal epithelial NOTCH1 as a protector for the development of colorectal adenocarcinoma in a murine model has been described." (PMID 34681094, 2021). "Finally, we found that the expression of Notch-1 is significantly reduced in human colorectal mucinous adenocarcinoma when compared to colorectal adenocarcinoma." (PMID 30323897, 2018). "This might reflect cytoplasmic signal activation of Notch1 for regulating the growth of colorectal adenocarcinomas." (PMID 24312514, 2013).
dementia (4 papers, 2016 to 2026). Loss of intellectual abilities interfering with an individual's social and occupational functions. "Based on the late-onset of the AD-like symptoms, this mouse model appeared the most suitable to investigate changes in Notch1 signaling, particularly, taken that this intracellular cascade has been previously implicated in dementia." (PMID 27364742, 2016). "Interestingly, olfaction and memory are brain functions, that are progressively affected in dementia making the case for a possible involvement of Notch1 in the neurological deficits associated with the disease." (PMID 27364742, 2016). "We measured the levels of soluble Notch1 (sNotch1) in the plasma samples from 72 dementia patients (average age 75.1 y), 89 subjects with amnestic mild cognitive impairment (MCI) (average age 73.72 y), and 150 cognitively normal controls (average age 72.34 y)." (PMID 31770379, 2019). "The present study demonstrates that the plasma level of Notch1 correlates with cognitive decline in patients with dementia." (PMID 31770379, 2019). "Despite there is no common consensus on whether Notch1 signaling is augmented or reduced in dementia, all these studies suggest a potential involvement of this signaling pathway in the progression of the diseases." (PMID 27364742, 2016).
diabetic retinopathy (4 papers, 2021 to 2023). "Likewise, SIRT1/Notch1 modulation was earlier stated to improve inflammation and oxidative stress in the model of diabetic retinopathy in rats." (PMID 37934372, 2023). "Notch1 represents a crucial pathway regulating angiogenesis in diabetic retinopathy." (PMID 36291965, 2022).
dilated cardiomyopathy (4 papers, 2014 to 2025). Cardiomyopathy which is characterized by dilation and contractile dysfunction of the left and right ventricles. "By doing so, Notch1 exerts control not only of heart homeostasis but also of its adaptation to stresses and injuries: Notch1 inhibition in newborn healthy mice causes a 56% reduction of cardiomyocytes and induces dilated cardiomyopathy." (PMID 25629006, 2014). "Moreover, a number of experimental studies have shown that blocking the Notch1 pathway in mice with γ-secretase inhibitors increases both the morbidity and mortality associated with dilated cardiomyopathy." (PMID 38841263, 2024).
Fanconi anemia (4 papers, 2017 to 2023). Fanconi anemia (FA) is a hereditary DNA repair disorder characterized by progressive pancytopenia with bone marrow failure, variable congenital malformations and predisposition to develop hematological or solid tumors. "Otherwise, in FANCA-mutated Fanconi anemia characterized by pancytopenia and chromosomal instability due to dysregulated DNA repair, Notch1 overexpression facilitated defective hematopoietic cell proliferation." (PMID 36497257, 2022). "Mutations in PTEN, SOX2 and NOTCH1, which are also frequently associated with SCLC, and BRCA1/2 or other known Fanconi anaemia genes were also not detected." (PMID 29387807, 2017).
fibrosis (4 papers, 2016 to 2021). the formation of excess fibrous connective tissue in an organ or tissue in a reparative or reactive process. "Our study showed that Notch1 signaling was inhibited in T2DM mice with MI and that cardiac fibrosis or cardiac dysfunction increased." (PMID 34957094, 2021). "Notch-2, rather than Notch-1, plays an important role in generating tubulointerstitial fibrosis in our myofibroblast and UUO models." (PMID 29101337, 2017). "Moreover, we found that the inhibition of Notch1/Jagged1 signaling by DAPT could block macrophage M2 polarization and ameliorate liver granulomata and fibrosis in a murine model of Schistosomiasis japonica." (PMID 27875565, 2016).
gallbladder cancer (4 papers, 2019 to 2025). "In summary, ZFP64 promotes the progression of gallbladder cancer through activating the Notch1 signaling pathway." (PMID 37760477, 2023). "Research has shown that gallbladder cancer cells-derived exosomes can transfer lncRNA TRPM2-AS to human umbilical vein endothelial cells (HUVECs), thereby activating the NOTCH1 signaling pathway and ultimately facilitating angiogenesis in gallbladder cancer." (PMID 41179289, 2025).